TSPO (translocator protein)
Diseases named in the same sentence as TSPO in open-access papers (continued):
Sharing a sentence is not in itself a finding about the gene and the disease.
intracerebral hemorrhage (4 papers, 2016 to 2025). A cerebrovascular disorder characterized by bleeding into one or both cerebral hemispheres including the basal ganglia and the cerebral cortex. "We found significant overlap with gene lists associated with intracerebral hemorrhage (ICH) volume (SERPINB1, TSPO, and GSR) and absolute perihematomal edema (PHE; TSPO and GSR) volume in ICH patients." (PMID 41353157, 2025). "Herein, we investigate whether [125 I]IodoDPA-713 can be used to monitor the changes in TSPO expression in a preclinical model of intracerebral hemorrhage." (PMID 29520214, 2018). "Given the role of TSPO in neuroinflammation, herein we investigate whether a second-generation TSPO ligand, [125 I]IodoDPA-713 can be used to monitor the changes in TSPO expression in a preclinical model of intracerebral hemorrhage." (PMID 29520214, 2018).
lymphoma (4 papers, 2015 to 2026). A malignant (clonal) proliferation of B- lymphocytes or T- lymphocytes which involves the lymph nodes, bone marrow and/or extranodal sites. "A similar function has been ascribed to TSPO, the third most downregulated gene, additionally known to be highly expressed in lymphoma cells and to induce resistance to apoptosis and H2O2-induced cytotoxicity in hematopoietic cell lines." (PMID 33669329, 2021).
major depressive episode (4 papers, 2015 to 2025). "For example, individuals experiencing a major depressive episode present enhanced positron emission topography labeling of the translocator protein (TSPO), a putative marker of neuroinflammation and microglia activation." (PMID 29114211, 2017). "The involvement of microglia in MDD pathophysiology is confirmed by a recent PET study investigating translocator protein (TSPO) binding as a biomarker for microglial activity in MDD patients with an active major depressive episode." (PMID 26654099, 2015). "TSPO distribution volume significantly increased during major depressive episodes." (PMID 41301474, 2025).
neuroblastoma (4 papers, 2019 to 2020). Neuroblastoma (NB) is the most common solid, extracranial childhood tumor. "Another publication revealed TSPO as a critical, differentially expressed gene in neuroblastoma with cyclin-dependent kinase (CDK) 2 silencing." (PMID 33066460, 2020). "The effect of TSPO depletion on ΔΨm has been reported in mouse MA-10 cells, fibroblasts, human neuroblastoma cells and mouse and rat cardiomyocytes." (PMID 33383772, 2020). "Over-activation of TSPO via these processes eventually lead to cell death in human neuroblastoma cells." (PMID 31295884, 2019). "Moreover, TSPO was shown to be involved in the OMM-based pathway to control intracellular Ca2+ dynamics and redox transients in human SH-SY5Y neuroblastoma cells." (PMID 33383772, 2020). "Most of our predictions, including the CNR2 inhibitor GW405833, the UGCG inhibitor DL-PDMP, the TSPO antagonist PK11195, and the MAPK8/JNK inhibitor AS601245, downregulated the expression of genes induced during the cell cycle, implicating effects on neuroblastoma cell growth." (PMID 31900415, 2020).
oligodendroglioma (4 papers, 2016 to 2023). A well-differentiated (WHO grade II), diffusely infiltrating neuroglial tumor, typically located in the cerebral hemispheres. "In addition, the higher microglial TSPO and perhaps a varying affinity across oligodendrogliomas may contribute to the distinct kinetic." (PMID 27077069, 2016). "All patients with newly onset HGGs were positive for both [18F]-FET and [18F]-DPA-714 uptake, both TSPO and amino-acid PET were negative in one case, and the [18F]-FET result was positive and [18F]-DPA-714 negative in two cases (i.e., one grade III and one grade II oligodendroglioma)." (PMID 37238297, 2023).
post-traumatic stress disorder (4 papers, 2014 to 2025). An anxiety disorder precipitated by an experience of intense fear or horror while exposed to a traumatic (especially life-threatening) event. "Patients with posttraumatic stress disorder have lower levels of TSPO, and stimulation of TSPO improved behavioral deficits in a mouse model of posttraumatic stress disorder (73, –, 75)." (PMID 24877623, 2014). "Increased inflammation is associated with decreased HPC volume in people with post-traumatic stress disorder (PTSD) and major depressive disorder (MDD), and positron emission tomography (PET) has shown increased binding of TSPO, a marker of neuroimmune activation in the HPC of people with MDD." (PMID 40038827, 2025).
type 2 diabetes (4 papers, 2018 to 2024). "The post hoc pairwise comparison between traumatic patients with coma and controls only identified a significant TSPO levels difference in the mPFC (P-value = 0.02)." (PMID 38412555, 2024). "Hence, our findings emphasize the need for future longitudinal studies tracking brain serial TSPO levels from coma onset in relation to neurological performance over time, aiming to understand whether these neuroimmune signatures persist, progress and/or warrant neuroimmune-modulating interventions." (PMID 38412555, 2024).
anxiety disorder (3 papers, 2013 to 2025). A category of psychiatric disorders which are characterized by anxious feelings or fear often accompanied by physical symptoms associated with anxiety. "The pharmacological activation of the cholesterol-binding Translocator Protein (TSPO) leads to an increase of endogenous steroids and neurosteroids determining benefic pleiotropic effects in several pathological conditions, including anxiety disorders." (PMID 26750656, 2016). "As such, the future investigation of TSPO-targeted neurosteroids and other GABA receptor modulators as potential treatment options for anxiety disorders is warranted, since novel pharmaceutical agents that target the GABA system may offer more effective outcomes with fewer side effects." (PMID 40508224, 2025).
aortic aneurysm (3 papers, 2014 to 2020). A ruptured aneurysm located in the wall of the proximal portion of the descending aorta proceeding from the arch of the aorta. "High TSPO radioligand uptake to vessel wall has been observed in the same model as in the current study and in a rat model of aortic aneurysm." (PMID 29950954, 2018). "In conjunction with increased TSPO gene expression and protein expression in AAA, this data supports the role of 18 F-FDG and TSPO radioligands for the assessment of aortic wall inflammation during the development of aortic aneurysms in patients." (PMID 26055934, 2014).
asthma (3 papers, 2017 to 2024). "Indeed, TSPO exhibited downregulated expression in patients with acute exacerbations of COPD and a protein-protein interaction network analysis revealed that TSPO could be implicated in development and/or progression of asthma in children." (PMID 29114179, 2017). "Our study is one of the few studies available that explore the relation between asthma and TSPO as well as its ligands." (PMID 38641850, 2024). "Both the TSPO agonist Ro5-4864 and the antagonist PK 11,195 exerted the mitochondrial protective and anti-apoptotic effects and exerted a therapeutic effect on asthma mice." (PMID 38641850, 2024). "Interestingly TSPO, a mitochondrial transport protein, has been suggested as a potential target for asthma in children, based on protein-protein interaction network predictions supported by differential expression analysis of expression profiling data." (PMID 29320511, 2018).
cardiac ischemia (3 papers, 2018 to 2022). "Indeed, TSPO is upregulated in chronic heart failure, and inhibition of TSPO is cardioprotective after myocardial ischemia." (PMID 36279013, 2022). "Similarly, TSPO targeting by 3,5-Seco-4-nor-cholestan-5-one oxime-3-ol (TRO40303) was tested in clinical trials, due to promising cardioprotective effects on a rat model of cardiac ischemia." (PMID 32635556, 2020).
demyelination (3 papers, 2019 to 2022). "The present study demonstrates the temporal, regional and cellular patterns of TSPO expression during the progression of cuprizone-induced demyelination in the mouse brain." (PMID 30696113, 2019). "In another study on the source of TSPO cells, the researchers found that in neurotoxicant-induced animal model of demyelination, TSPO signal was initially provided by microglia, while in a later stage (such as 6 weeks later), the signal source of TSPO was mainly from astrocytes." (PMID 34873637, 2022). "Two of these studies were longitudinal and identified that two weeks after induction of demyelination in a cuprizone-induced demyelination model, TSPO-positive cells were predominantly microglia, whereas six-weeks after demyelination induction TSPO-positive cells were predominantly astrocytes." (PMID 31261683, 2019). "To determine whether recruited monocytes, in addition to microglia, express TSPO, we combined the toxin-induced demyelination model cuprizone with the autoimmune EAE model (i.e., Cup/EAE)." (PMID 30696113, 2019). "The purpose of this study was to assess the feasibility of utilizing PET imaging with the TSPO tracer, [18F]-GE180, to detect histopathological changes during experimental demyelination, and to determine which cell types express TSPO." (PMID 30696113, 2019). "Although the densities of the GFAP+ cells gradually increased in the corpus callosum and cortex during the course of cuprizone-induced demyelination, a significant proportion of the GFAP+ cells were TSPO-negative in the control and cuprizone-exposed mice." (PMID 30696113, 2019).
diabetic neuropathy (3 papers, 2011 to 2020). A chronic, pathological complication associated with diabetes mellitus, where nerve damages are incurred due to diabetic microvascular injury involving small blood vessels that supply these nerves, resulting in peripheral and/or autonomic nerve dysfunction. "More researches have shown that TSPO activation was effective in ameliorating the severity of diabetic neuropathy through a local increase of neuroactive steroid levels." (PMID 27886206, 2016). "Some authors have reported protective effects of TSPO agonists in experimental diabetic neuropathy, suggesting, hypothetically, reparative actions of brain TSPO in such a disease." (PMID 21299850, 2011). "Altogether these observations suggest that activation of LXR or TSPO, by increasing the levels of neuroactive steroids in the sciatic nerve, exerts neuroprotective effects in diabetic neuropathy and consequently may represent an alternative to the direct treatment with neuroactive steroids." (PMID 33256238, 2020).
glaucoma (3 papers, 2012 to 2022). Increased pressure in the eyeball due to obstruction of the outflow of aqueous humor. "The tight correlation of microglia reactivity with TSPO expression was also identified in the genetic mouse model of myosin VII deficiency that mimics both features of retinal dystrophies and glaucoma." (PMID 26527153, 2015).
Immunodeficiency (3 papers, 2021 to 2025). Failure of the immune system to protect the body adequately from infection, due to the absence or insufficiency of some component process or substance. "Our data suggests that mitochondrial reprogramming associated with specific responses to different pathogens could influence the ability to reverse SIFD-linked immunodeficiency, through the targeting of TSPO expression." (PMID 41019077, 2025).
melanoma (3 papers, 2018 to 2025). A malignant, usually aggressive tumor composed of atypical, neoplastic melanocytes. "A shift from homogenous cytoplasmic expression of TSPO to nuclear and perinuclear expression is observed in melanoma as it progresses to more advanced stages." (PMID 30044440, 2018).
metabolic syndrome (3 papers, 2013 to 2024). A cluster of metabolic risk factors for CARDIOVASCULAR DISEASES and TYPE 2 DIABETES MELLITUS. "The major diseases and disorders predicted for TSPO were inflammatory, neuroinflammatory and psychiatric diseases and disorders, cancer, and metabolic syndrome." (PMID 34212002, 2021). "Taken together, the interaction of both TSPOAP1 and TSPO with these proteins supports the overlapping functions of TSPOAP1 and TSPO, including shared roles in inflammation, oxidative stress, metabolic syndrome, and cancer." (PMID 34212002, 2021). "This combined with effects of the TSPO ligand PK11195 on the expression of metabolic genes in WAT provides important initial evidence that TSPO may be a potential therapeutic target for Metabolic Syndrome." (PMID 24260329, 2013). "Combining these pieces of information from the major signalling pathways of TSPOAP1 and TSPO, we can state that both proteins seem majorly involved in inflammation cascades and orchestrate a pivotal role in inflammation, oxidative stress, aging, cancer, and metabolic syndrome." (PMID 34212002, 2021).
multiple system atrophy (3 papers, 2017 to 2023). Multiple system atrophy (MSA) is a neurodegenerative disorder characterized by autonomic failure (cardiovascular and/or urinary), parkinsonism, cerebellar impairment and corticospinal signs with a median survival of 6-9 years. "Conversely, when lesions are present with antigenic alpha-synuclein, as in cases of human multiple system atrophy, post-mortem tissue had a 6-fold increase in MHCII and 2-fold increase in TSPO relative to controls." (PMID 32990808, 2020). "As for other neurodegenerative conditions, TSPO PET has been successfully applied in synucleinopathies, such as in DLB, PD, and PD with dementia; in FTD176; in atypical parkinsonisms such as multiple system atrophy (MSA), CBD, and PSP177–179; and in prion diseases, such as Creutzfeldt-Jakob disease." (PMID 29071066, 2017).
ocular hypertension (3 papers, 2012 to 2020). Abnormally high intraocular pressure. "Modeling ocular hypertension in vitro increased the expression of TSPO and MHC‐II in retinal neural cells, consistent with a response of microglia to elevated pressure." (PMID 30667095, 2019). "In a model of induced ocular hypertension (OHT), microglia were shown to be reactive as detected by the increased expression of translocator protein (TSPO), major histocompatibility complex class II (MHC-II) and pro-inflammatory mediators in the retina early after OHT induction." (PMID 32218163, 2020).
Parkinsonism (3 papers, 2020 to 2021). Characteristic neurologic anomaly resulting from degeneration of dopamine-generating cells in the substantia nigra, a region of the midbrain, characterized clinically by shaking, rigidity, slowness of movement and difficulty with walking and gait. "Having observed that SH-SY5Y cells recapitulate the upregulation of TSPO observed in vivo, we administered two other PD-linked neurotoxins, chosen for their ability to induce ERK-dependent autophagy and Parkinsonism in vivo." (PMID 33664474, 2021).
pneumonia (3 papers, 2017 to 2021). An acute, acute and chronic, or chronic inflammation focally or diffusely affecting the lung parenchyma, caused by an infection in one or both of the lungs (by bacteria, viruses, fungi, or mycoplasma.). "In vivo imaging of TSPO in the peripheral tissues can also help to detect inflammation, such as pneumonia." (PMID 33725191, 2021).
status epilepticus (3 papers, 2012 to 2021). Status epilepticus is defined as a continuous seizure lasting more than 30 min, or two or more seizures without full recovery of consciousness between any of them. "PET‐derived measures of neuroinflammation have been validated in rat models of TLE—kainic acid‐induced status epilepticus—where increased TSPO expression has been associated with increased microglial activation determined using immunohistochemistry." (PMID 33605514, 2021). "Particularly, TSPO overexpression was observed after the induction of status epilepticus in several brain regions with a well-established role in seizure generation and/or propagation." (PMID 23136853, 2012). "In a rat model of status epilepticus (SE), TSPO PET using 18F-DPA-714 tracer showed increased uptake within the limbic system even in the hippocampus and reached its maximum at 7 days after SE, while TSPO binding declined to the baseline levels at 14-16 weeks post-SE." (PMID 34976232, 2021). "Interestingly, the severity of the status epilepticus corresponded with the extent of TSPO overexpression." (PMID 23136853, 2012).
steatosis (3 papers, 2021 to 2025). Increased lipid within the cytoplasm of cells. "Our results are not only in agreement with earlier studies that impaired autophagy is linked to the initial development of hepatic steatosis and the progression of steatosis to liver injury, but underscore the indispensable role of TSPO in maintaining hepatic lipid metabolism." (PMID 40195072, 2025). "Translocator protein (TSPO) regulates steatosis in nonalcoholic fatty liver disease." (PMID 36344742, 2022).
vasculitis (3 papers, 2014 to 2020). "In the PET imaging of vascular inflammation with TSPO-targeting tracers, 11C-(R)-PK11195 has shown great potential especially in imaging vasculitis." (PMID 29950954, 2018).
Arrhythmia (2 papers, 2015 to 2018). Any cardiac rhythm other than the normal sinus rhythm. "As will be highlighted below, TSPO-mediated regulation of RIRR can influence postischemic arrhythmias directly via IMAC and indirectly via PTP." (PMID 25918579, 2015). "In addition to serving as a biomarker of inflammatory disease, TSPO actively participates in the regulation of non-myocyte cellular functions that likely influence arrhythmia vulnerability." (PMID 30416455, 2018). "Although earlier studies showed that TSPO-acting ligands which reduced ROS levels were effective in abolishing metabolic and electrophysiological oscillations, their impact on arrhythmias in clinically relevant scenarios was not established until more recently." (PMID 25918579, 2015).
autoimmune myocarditis (2 papers, 2018 to 2021). Autoimmune myocarditis is an autoimmune disease that affects the heart. "Here, we describe the in vivo evaluation of two classes of TSPO-selective PET radiotracers for detecting myocardial inflammatory foci by assessing TSPO expression in a rat model of experimental autoimmune myocarditis (EAM)." (PMID 29342117, 2018). "Here, we evaluated TSPO overexpression in a rat model of experimental autoimmune myocarditis (EAM) compared to healthy rats using two TSPO radiotracers, [18F]fluoromethyl-PBR28 ([18F]1) and [18F]CB251 ([18F]2)." (PMID 29342117, 2018).
brain glioma (2 papers, 2021 to 2023). A malignant glioma that involves the brain. "PET imaging of TSPO is intensively used to image neuroinflammation in a diverse range of neurodegenerative conditions and malignant brain gliomas, as TSPO is overexpressed in activated microglia and macrophages." (PMID 38162485, 2023). "Apart from brain gliomas, only a few preclinical studies have evaluated TSPO-PET tracers in peripherally located tumours." (PMID 33340054, 2021). "Translocator protein (TSPO)-targeting positron emission tomography (PET) imaging is currently mainly used for imaging neurodegenerative diseases and brain gliomas as TSPO is considered a biomarker of neuroinflammation and microglial activation." (PMID 33340054, 2021).
breast tumor (2 papers, 2016 to 2024). "A study on its occurrence in neoplastic cells and tumor macrophages of mouse xenografts of human breast tumor cell lines showed that TSPO concentration in various cell types within the tumor contributed to the total TSPO expression." (PMID 38585455, 2024).
cervical cancer (2 papers, 2015 to 2022). A primary or metastatic malignant neoplasm involving the cervix. "Genes PFDN4, CASP1, PLCE1, ICOSLG, GADD45G, SMARCA2, and TSPO are located in different chromosomes, and there are reports for changes in each one of these chromosomes in cervix cancer, for examples the reader is refer to:." (PMID 26388997, 2015).